IL6 (interleukin 6)
Diseases named in the same sentence as IL6 in open-access papers (continued):
Sharing a sentence is not in itself a finding about the gene and the disease.
cellulitis (3 papers, 2013 to 2023). Inflammation of the dermis and subcutaneous tissues caused by a bacterial infection. "For example, there was a case report of a child with autoantibodies against IL-6 who suffered from cellulitis and subcutaneous abscesses caused by S. aureus." (PMID 23936360, 2013). "High levels of anti-IL-6 autoantibodies were also noted in a child who developed an acute VZV infection complicated by multiple cellulitis lesions and subcutaneous Staphylococcus aureus abscesses." (PMID 26482341, 2015).
cervical adenocarcinoma (3 papers, 2014 to 2024). An adenocarcinoma arising from the cervical epithelium. "Overall, miR‐9 has the potential to suppress tumors in cervical adenocarcinoma and suggests repression of tumorigenesis through inhibition of the IL‐6/Jak/STAT3 pathway." (PMID 39263322, 2024). "To understand the Cervical Adenocarcinoma response to IL-6 stimulation, we performed a detailed time course analyzing the phosphorylation events in HeLa cells." (PMID 24533454, 2014). "However, a study demonstrated the downregulation of miR‐9 in cervical adenocarcinoma due to frequent hypermethylation, exerting a tumor suppressor role by targeting various genes, including IL‐6." (PMID 39263322, 2024). "Collectively, these results showed that IL-6 is a potent inducer STAT3 signaling, while it has a weaker effect on the phosphorylation of Akt and ERK in Cervical Adenocarcinoma." (PMID 24533454, 2014).
childhood asthma (3 papers, 2015 to 2023). "RSV infection induces chemokines such as RANTES, MIP-α, and IL-6 which are associated with childhood asthma and have side effects on type I IFN induction." (PMID 26557722, 2015).
cholera (3 papers, 2015 to 2020). "To better understand what drives the activation of IL-23 production after exposure to live V. cholerae, we compared its expression and secretion with those of additional cytokines known to be activated in cholera, including IL-1β and IL-6." (PMID 31434744, 2019). "Cholera toxin also suppresses production of IL-12 by bone marrow-derived DC, which drives Th1 responses 47, and induces production of IL-6 and IL-10 important in Th2 differentiation." (PMID 26130503, 2015). "To distinguish additional innate immune pathways differentially activated by exposure to live compared to heat-inactivated V. cholerae, we next measured responses to IL-6, another proinflammatory cytokine that was previously found to be upregulated during acute cholera." (PMID 31434744, 2019).
chronic kidney failure (3 papers, 2014 to 2024). "In an in vivo study involving uremic rats with chronic kidney failure, it was observed that rats fed a diet containing 0.1% Mg experienced increased pro-inflammatory cytokines like TNF-α, IL-1β, and IL-6, resulting in the induction of oxidative stress." (PMID 39200118, 2024). "Disease pathway analysis showed IL6, EPO, ADIPOQ and CCR2 to be involved in chronic kidney failure." (PMID 25280384, 2014).
chronic mucocutaneous candidiasis (3 papers, 2012 to 2023). "One is a clinical study reporting that PBMCs from dectin-1−/− women exhibited impaired IL-6 and IL-17 production and in turn, increased susceptibility to familial chronic mucocutaneous candidiasis and RVVC." (PMID 23050010, 2012).
chronic venous insufficiency (3 papers, 2022 to 2023). Chronic form of venous insufficiency (disease). "Likewise, in patients suffering from chronic venous insufficiency and treated for three months with diosmin at a total daily dose of 1200 mg, a decrease in the proinflammatory factors TNF-α, IL-6, VEGF-A, and VEGF-C, which were associated with a reduction in mean leg circumference, was observed." (PMID 37513462, 2023).
CNS lymphomas (3 papers, 2021 to 2026). "While the diagnostic value of cerebrospinal fluid (CSF) IL-10 and IL-10/IL-6 ratios has been established in primary CNS lymphoma (PCNSL), their utility in predicting CNS relapse in SCNSL remains underexplored." (PMID 40881684, 2025).
Coats disease (3 papers, 2020 to 2021). Coats disease (CD) is an idiopathic disorder characterized by retinal telangiectasia with deposition of intraretinal or subretinal exudates, potentially leading to retinal detachment and unilateral blindness. "We found that the concentrations of 8 out of 22 cytokines (VEGF, IL-6, IL-8, MCP-1, MIP-1α, IP-10, VACM-1 and ICAM-1) were significantly increased in the AH of eyes with Coats disease." (PMID 32370768, 2020). "Of the 22 measured cytokines, the concentrations of 8 cytokines (VEGF, IL-6, IL-8, MCP-1, MIP-1α, IP-10, VCAM-1 and ICAM-1) were significantly higher in the Coats disease group than in the control group (all P < 0.002)." (PMID 32370768, 2020). "The concentrations of 8 cytokines (VEGF, IL-6, IL-8, MCP-1, MIP-1α, IP-10, VCAM-1 and ICAM-1) were significantly higher in the Coats disease group than in the control group (all P < 0.002)." (PMID 32370768, 2020). "Although the number of pooled studies were relatively small, increased IL-6 level was also observed in RD, PVR, ROP and Coats’ disease." (PMID 33060644, 2020). "Interleukin (IL)-6, IL-1β and monocyte chemoattractant protein (MCP)-1levels in AH were higher in Coats disease group than the control group, and MCP-1 level was strongly associated with the severity of retinal exudation." (PMID 32370768, 2020). "Various cytokines in the AH, including elevated VEGF, IL-6, IL-8, MCP-1, MIP-1α, IP-10, VCAM-1 and ICAM-1, may be involved in the pathogenesis and progression of Coats disease." (PMID 32370768, 2020).
cocaine addiction (3 papers, 2015 to 2023). "The IL-6 concentrations were also significantly affected by history of cocaine addiction (F1,122 = 13.46, p < 0.001) and sex (F1,122 = 11.05, p = 0.001)." (PMID 25762940, 2015). "The plasma concentrations of interleukin 1-beta (IL-1β), IL-6, IL-10, and tumor necrosis factor-alpha (TNFα) were affected by history of cocaine addiction and sex." (PMID 25762940, 2015). "In summary, this study identified four key genes (FOS, IL6, EGR1, and JUN) that might be involved in cocaine addiction mechanisms and had potential roles as biomarkers and therapeutic targets for cocaine addiction." (PMID 37469839, 2023). "Four key genes (JUN, FOS, EGR1, and IL6) were identified and well validated using CTD database correlation analysis, text mining, independent dataset analysis, and enrichment analysis methods, and they might serve as biomarkers of cocaine addiction." (PMID 37469839, 2023).
cocaine use disorder (3 papers, 2018 to 2025). A substance-related disorder that involves the recurring use of cocaine despite negative consequences. "In exploratory human trials—for instance, a high-dose CBD study in people with a cocaine use disorder—high systemic exposure was linked with reductions in IL-6 and VEGF-A and shifts in immune cell subsets, notwithstanding heterogeneity in plasma concentrations and sensitivity to analytical choices." (PMID 41373770, 2025). "The results of this research surpass current basic knowledge and take on a clear translational relevance, since IL-6 levels have been found to be altered in humans under conditions of social stress, and even more so in those with cocaine use disorders." (PMID 30557308, 2018).
Coccidioides infection (3 papers, 2021 to 2025). "In response to Coccidioides infection, Spp1+ macrophages express high levels of pro-inflammatory (Nos2, Tgfb1, Il1β, and Il6) and fibrotic/wound healing associated genes (Inhba, Spp1, Arg1, Pdgfb, and Fn1)." (PMID 40704794, 2025). "Dogs with coccidioidomycosis produced higher coccidioidal stimulated supernatant concentrations of TNF-α (p = 0.003), IL-6 (p = 0.04), IFN-γ (p = 0.03), MCP-1 (p = 0.02), IL-10 (p = 0.02), and lower IL-8 (p = 0.003) than controls." (PMID 36836327, 2023). "The monocyte to macrophage differentiation in response to Coccidioides infection, although not previously measured, is consistent with prior studies that found high IL-6, IL-12, TNF and MIP-2 production by Coccidioides-infected peritoneal macrophages." (PMID 34436169, 2021). "Likewise, dogs with coccidioidomycosis produced higher concentrations of TNF-α (p < 0.0001), IL-6 (p < 0.0001), GM-CSF (p = 0.03), IL-8 (p = 0.02), IFN-γ (p = 0.03), KC-like (p = 0.01), MCP-1 (p = 0.01), and IL-10 (p = 0.0004) with coccidioidal stimulation compared with unstimulated control." (PMID 36836327, 2023).
cognition (3 papers, 2019 to 2023). Intellectual or mental process whereby an organism becomes aware of or obtains knowledge. "Plasma IL-6 level was inversely with hippocampal grey matter volume, which was a structure critical for memory formation and associated with cognition decline." (PMID 31296192, 2019).
colonic polyp (3 papers, 2016 to 2024). "Using univariable MR analyses and Bayesian model averaging, we identified MIG, IL-18, and IL-2ra as the top three causes of gastric polyp, MIP1b and IL-6 as the top two protective factors for colonic polyp, and an inverse association between IL-9 and gallbladder polyp." (PMID 39439893, 2024). "Regarding for colonic polyp, the two prioritized protective factors we identified were IL-6 and MIP1b, respectively." (PMID 39439893, 2024). "The three highest-ranked causal circulatory cytokines for colonic polyp were: MIP1b (MIP = 0.752, MACE = −0.033), IL-6 (MIP = 0.196, MACE = −0.012), IL-18 (MIP = 0.112, MACE = 0.004)." (PMID 39439893, 2024). "The two circulatory cytokines causally associated with colonic polyp were: macrophage inflammatory protein-1b (MIP1b, IVW—OR: 0.956, 95%CI: 0.927–0.987, p = 0.005; WM—OR: 0.954, 95%CI: 0.916–0.993, p = 0.021) and interleukin-6 (IL-6, IVW—OR: 0.931, 95%CI: 0.870–0.995, p = 0.035)." (PMID 39439893, 2024). "A recent paper showed that enhanced IL-6 in Nlrx1−/− mice is consequential, as anti-IL6R therapy completely reduced colon polyps in these animals." (PMID 27105514, 2016). "An animal study observed that the size of colonic polyps decreased significantly when IL-6 expression was absent." (PMID 39439893, 2024).
complex regional pain syndrome type 1 (3 papers, 2006 to 2022). "Patients with algodystrophy present an amplified and persistent activation of the innate immune system, with subsequent proliferation of keratinocytes and release of proinflammatory cytokines including interleukin (IL)-6, IL-1β, and tumor necrosis factor-α (TNF-α)." (PMID 36120194, 2022). "In an earlier study, levels of the proinflammatory cytokines TNF-α and IL-6 are higher in blisters fluid from the complex regional pain syndrome type 1 (CRPS1) side obtained at 6 and 30 months (median) after the initial event." (PMID 18596918, 2008). "Inflammatory processes are known to be involved at least in theearly phase of complex regional pain syndrome type 1 (CRPS1).Blister fluid obtained from the involved extremities displayedincreased amounts of proinflammatory cytokines IL-6 and TNFαcompared with the noninvolved extremities." (PMID 16864900, 2006).
corneal disease (3 papers, 2021 to 2024). "In this study, we evaluated the cytokine profiles of IL-2, IFN-γ, ICAM-1, IL-5, IL-6, IL-8, IL-10, IL-1β, MCP-1, IL-17A, IP-10, G-CSF, and VEGF-A in the AqH of BK patients before and after DMEK and in a control group without corneal disease." (PMID 34426617, 2021).
coronary vasospasm (3 papers, 2021 to 2025). Sudden coronary artery smooth muscle contraction leading to lumen constriction and decreased blood flow. "In one case, coronary vasospasm was induced by intracoronary injection of acetylcholine, and functional disturbance of the vascular endothelium associated with increased IL-6 levels is speculated as an underlying mechanism of coronary vasospasm." (PMID 34167480, 2021). "In addition, high-sensitivity CRP increased IL-6 level, p38MAPK expression, and monocyte activation, which contribute to coronary artery spasm, whereas the overexpression of the monocytic α7 n Ach receptor decreases oxidative stress and inflammation-associated coronary artery spasm." (PMID 35425785, 2022).
Cryptosporidium infection (3 papers, 2018 to 2024). "At the same time, TNF-α has been found as the central mediator of inflammation to induce the secretion of IL-6, IL-1 and other inflammatory factors, causing the inflammatory response after Cryptosporidium infection in mice." (PMID 38914662, 2024). "Therefore, it can be concluded that oxymatrine can regulate the inflammatory factors TNF-α, NF-κB, and IL-6 through the TNF/NF-κB signaling pathway for the treatment of cryptosporidiosis." (PMID 38914662, 2024). "However, the expression of TNF-α, NF-κB and IL-6 was reversed after treated with oxymatrine, suggesting that oxymatrine can achieve the therapeutic effect of cryptosporidiosis through the TNF/NF-κB signaling pathway." (PMID 38914662, 2024). "In vivo experiments preliminarily verified that oxymatrine can control intestinal inflammation by regulating the TNF/NF-κB signaling pathway and down-regulating the expression of TNF-α, NF-κB, and IL-6, thereby contributing to the treatment of cryptosporidiosis." (PMID 38914662, 2024). "In order to investigate the mechanism of oxymatrine in treating cryptosporidiosis, we constructed a target-KEGG network and identified the top 5 involved genes, namely RELA, AKT1, TNF, CASP3, and IL-6." (PMID 38914662, 2024). "First, we performed a target database search to obtain a total of 47 intersecting targets of oxymatrine for the treatment of cryptosporidiosis, including the core targets of ALB, IL-6, TNF, AKT1, CASP3, and SRC." (PMID 38914662, 2024). "SMC administration also reduced cytokines production (SAP, TNF-α, IL-6, and IFN-γ) mediated by Cryptosporidium infection in contrast to the infected untreated group." (PMID 33076496, 2020). "In accordance with previous data, the immune response during Cryptosporidium infection presented by an increasing expression of immune mediators such as TNF-α, IL-6, IFN-γ by T-helper cell (Th1) particularly protect against intracellular infections including C. parvum." (PMID 33076496, 2020).
cutaneous T cell lymphoma (3 papers, 2012 to 2021). "In cutaneous T-cell lymphoma, for example, IL-3, IL-4, IL-6, and IL-10 synthesized by T-cells promote the secretion of Th2 cytokines particularly IL-6." (PMID 29850592, 2018).
cystic kidneys (3 papers, 2021 to 2025). "This is the first study that reveals that abnormal expression of xFOSL1 caused the formation of dilated pronephric tubule, resembling renal cyst observed in JSRD, downstream of IL-6/JAK/STAT3 signaling." (PMID 40570958, 2025). "Cytokines, such as TNF-α, IL-6, and MCP-1, play crucial roles in renal inflammation within cystic kidneys, which can regulate the recruitment of macrophages in Pkd1 mutant kidneys." (PMID 39456148, 2024). "In addition, we found that treatment with cystic cell exosomes increased the expression of TNF-α, IL-6, and MCP-1 in recipient cells and in cystic kidneys." (PMID 34315885, 2021).
diabetic encephalopathy (3 papers, 2016 to 2025). A brain disease that is characterized by functional impairment of cognition, cerebral signal conduction, neurotransmission and synaptic plasticity, and underlying structural pathology associated with diabetes. "Diabetic encephalopathy was characterized by robust neuroinflammatory activation, with pro-inflammatory cytokines significantly elevated: TNF-α (4.7-fold), IL-6 (3.8-fold), IL-1β (3.2-fold), and IFN-γ (2.9-fold) compared to controls." (PMID 40723442, 2025).
disseminated candidiasis (3 papers, 2006 to 2024). Systemic candidiasis occurs when Candida yeast enters the bloodstream and may spread (becoming disseminated candidiasis) to other organs, including the central nervous system, kidneys, liver, bones, muscles, joints, spleen, or eyes. "The reduced virulence of the ISW2 null mutant DRL6 in a mouse model of disseminated candidiasis was associated at day 2 PI with decreased up-regulation of IL-6, TNF-α, MIP1-α, and IL-10, cytokines and chemokines that are known to play a role in innate host defense against Candida in vivo." (PMID 27727302, 2016). "Here, we investigated the secretion of the inflammatory factor interleukin-6 (IL-6) in lymphoid organs in a mouse model of disseminated candidiasis." (PMID 38682948, 2024). "Both TNFα and IL-6 have been shown to be protective in the mouse model of disseminated candidiasis, suggesting that unmasking β-glucan could provoke a proinflammatory response and attenuate virulence in disseminated disease." (PMID 16652171, 2006).
diverticulosis (3 papers, 2014 to 2020). "We have previously shown that these are linked to increased mucosal expression of a range of pro-inflammatory mediators including TNFɑ, IL6, monocyte chemotactic peptide 1 (MCP1) and prostaglandin E (PGE) in diverticular disease." (PMID 31067253, 2019).
dysautonomia (3 papers, 2020 to 2024). An acute or chronic disorder, affecting the sympathetic or parasympathetic nervous system. "Intervention to IL-6 associated pathway may be a candidate strategy in managing dysautonomia in patients with FM." (PMID 32704114, 2020).
eosinophilic pneumonia (3 papers, 2020 to 2023). An inflammatory lung disorder characterized by an increased number of eosinophils in the lungs. "The main mechanism of acute eosinophilic pneumonia has been elucidated to be due to pro-inflammatory cytokines such as IL-5, IL-6, IL-7, and tumor necrosis factor." (PMID 32366239, 2020).
ependymoma (3 papers, 2015 to 2020). A WHO grade II, slow growing tumor of children and young adults, usually located intraventricularly. "In ependymomas and DIPG IL-6-JAK/STAT, IFN-γ, and TNF-α signaling were enriched." (PMID 28969007, 2017).
essential thrombocythemia (3 papers, 2015 to 2021). A chronic myeloproliferative neoplasm that involves primarily the megakaryocytic lineage. "The endogenous levels of IL-6 and soluble IL-6 receptor are also elevated in essential thrombocythemia (ET)." (PMID 26491227, 2015). "The mutual effects of Ruxolitinib and IL-6 have not been observed in MNC of essential thrombocythemia (ET) (not shown)." (PMID 34206393, 2021).
euthyroid sick syndrome (3 papers, 2008 to 2025). Abnormal thyroid function tests, low triiodothyronine with elevated reverse triiodothyronine, in the setting of non-thyroidal illness. "IL-6 is implicated in the pathogenesis of euthyroid sick syndrome." (PMID 40870417, 2025). "IL-6 elevation and euthyroid sick syndrome development are interconnected." (PMID 40870417, 2025). "Blocking with IL-6, however, failed to induce the euthyroid sick syndrome (also called NTIS) in animal models." (PMID 25174507, 2014).
experimental arthritis (3 papers, 2010 to 2023). ARTHRITIS that is induced in experimental animals. "Cytokines such as interleukin-1-beta (IL-1β), tumor necrosis factor-alpha (TNF-α), and interleukin-6 (IL-6) have been shown to display potent proinflammatory actions and to contribute to the pathogenesis of RA or experimental arthritis, particularly to cartilage and bone damages." (PMID 22414623, 2012).